IL10 (interleukin 10)
Diseases named in the same sentence as IL10 in open-access papers (continued):
Sharing a sentence is not in itself a finding about the gene and the disease.
diabetes (continued). "The CCS and EDS could successfully lower blood glucose, regulate lipid metabolism, lower the levels of total cholesterol (TC) and low-density lipoprotein cholesterol (LDL-C), reduce the expressions of interleukin-6 (IL-6) and interleuki n-10 (IL-10), and decrease diabetes-related liver damage." (PMID 38790786, 2024). "Similarly, our previous study showed that after phytohemagglutinin stimulation, the PBMCs of patients with diabetes expressed lower IFNγ and IL-10 levels; however, they had higher monocyte responsiveness, which is measured based on TNFα/IFNγ and IL-6/IFNγ ratios." (PMID 39062154, 2024). "Thus, the increase in IL-10 expression in more severe cases of diabetes could be a reaction to the metabolic stress resulting from ketoacidosis or hyperglycemia." (PMID 37189738, 2023). "This hypothesis is consistent with the low-level chronic inflammation that is a common feature of diabetes and with the negative association between IL-10 and diabetes that has been reported in other settings." (PMID 35206272, 2022). "Therefore, the aim of this study was to investigate the effect of orally administered Lactococcus lactis MG1363 FnBPA+ strains carrying plasmids encoding IL-4 and IL-10 in the streptozotocin- (STZ-) induced diabetes model and in nonobese diabetic (NOD) mice." (PMID 33604389, 2021). "In addition, a recent study has also reported that chronic inflammation as observable by altered levels of anti-inflammatory cytokine levels including IL-4 and IL-10 may play a predictive role in disorders such as type 2 diabetes mellitus development." (PMID 31991875, 2020). "Therefore, it is advisable to believe that IL-10 has a protective effect on diabetes." (PMID 33072216, 2020). "Furthermore, diabetes reduces the level of the anti-inflammatory cytokine IL-10." (PMID 30373222, 2018). "As we are interested in applying this novel immunization strategy to clinic, papillomavirus like particles are licensed in 2006, next we investigated whether autoimmune prone NOD mice were more likely to develop diabetes when IL10 signalling was blocked at the time of immunization." (PMID 28810829, 2017). "However, this association between IL-10 and diabetes is still less studied and there are no available prospective studies to support this association." (PMID 27527152, 2016). "The increased production of the IL-4 and the anti-inflammatory Th2-cytokine IL-10 in DENV-infected mononuclear cells of the diabetes in our study might result from a counterbalance to the comparatively highly produced pro-inflammatory cytokines/chemokines in the diabetic hosts." (PMID 24078930, 2013). "However, recent studies have shown that rather than promoting disease, cross-reactivity can suppress auto-immunity through regulatory function of HSP-reactive T-cells and IL-10 production as seen in case of adjuvant-induced arthritis and diabetes after HSP vaccination in animal models." (PMID 24303034, 2013). "L. casei induced production of higher levels of IL-10 while L. reuteri and L. plantarum induced higher levels of IL-12, corroborating previous findings showing that different strains of Lactobacilli differentially modulate expression of cytokines in DCs from B6 (diabetes-resistant) mice." (PMID 21716731, 2011). "In addition, the incidence of diabetes is enhanced in transgenic IL-10-NOD mice expressing IL-10 in the glucagon-producing α-cells of the pancreas, and adoptive transfers of prediabetic or diabetic wild-type NOD splenocytes into these transgenic IL-10-NOD mice accelerates diabetes." (PMID 21716731, 2011). "Carriage of the IL10 -592A-allele yielded an odds ratio of 0.60 (95% CI: 0.41-0.87; p=0.008) for RAO, and remained significant after adjusting for age, sex, arterial hypertension, hypercholesterolemia, smoking status and diabetes mellitus (odds ratio: 0.65; 95% CI: 0.44-0.97; p=0.036)." (PMID 17438520, 2007).
diabetes (continued). "After univariate analysis and LASSO regression, diabetes, dyspnoea, FET, IL-10, FDP, INR, and Pro-BNP were included in the multifactorial analysis." (PMID 41426569, 2025). "In the final model with all predictors, VIF’s were the following: age = 1.22, sex = 1.04, hypertension or CVD = 1.18, diabetes = 1.26, cancer = 1.01, IL-6 = 1.27, TNFR1 = 1.99, IL-1b = 1.04, TNF-a = 1.55, IL-10 = 1.11, GDF15 = 2.16." (PMID 41280118, 2025). "Investigating other immunological markers such as IL-10, tumor necrosis factor-α, T-regulatory cells, or IgA secretion represents a promising area for future research for better characterization of the immunomodulatory mechanisms by which probiotics could influence glycemic control in diabetes." (PMID 40422866, 2025). "In parallel, an anti-inflammatory effect of inulin administration on DPN in diverse stages of diabetes was unveiled in this study by reducing pro-inflammatory LPS, IL-6, TNF-α and IL-17A and elevating anti-inflammatory IL-10." (PMID 41264657, 2025). "Intriguingly, the hematopoietic depletion of NOD1 mitigated the diabetes-induced expression of CXCL1 and CXCL2; TNFα and IL10 remained unaffected." (PMID 38336763, 2024). "The expressions of IL17A, MMP2, IL10 and IL6 are up-regulated with diabetes that promote the progression of OP, whereas the expressions of FGF2 and VEGFA are down-regulated." (PMID 38250601, 2024). "Our study investigated the expression of IL-1β, IL-10, CYP2C8, CYP2C9, CYP2J2 and sEH in HBCs from patients with type 1 diabetes mellitus (T1DM) and gestational diabetes mellitus (GDM) compared to healthy controls using immunohistochemistry." (PMID 38590527, 2024). "A combination therapy of preproinsulin (PPI) and immunomodulators (TGFβ+IL10) orally delivered via genetically modified Salmonella and anti-CD3 promoted glucose balance in in NOD mice with recent onset diabetes." (PMID 38543910, 2024). "Here, we specifically detected reduced expressions of IL1β, IL6, IL10 and VEGF-A in M1/proinflammatory macrophages at the inflammatory stage in diabetes." (PMID 38270651, 2024). "The protective effects of IL-10 have also been reported in humans, as suggested by the strong correlation between increased IL-10 expression and the attenuation of insulin-dependent diabetes mellitus (DM)." (PMID 39125659, 2024). "Treatment with quercetin largely inhibited SARS-CoV-2 N protein-induced F4/80+ macrophages infiltrating the diabetic kidney and greatly suppressed the mRNA expression of IL-6, TNF-α, and MCP-1 while increasing the expression of IL-4 and IL-10 mRNA levels." (PMID 38022581, 2023). "In diabetes, IRF7 knockdown increases anti-inflammatory IL-10 production and decreases proinflammatory IL-6 level in bone marrow-derived macrophages." (PMID 36336986, 2023). "Here, we aim to investigate the relationship among exosomal miR‐let‐7c‐5p (or miR‐let‐7i‐5p), IL‐10 levels in plasma, and MCI in type 2 diabetes mellitus (T2DM) patients via the present cross‐sectional research." (PMID 37532673, 2023). "In multivariate logistic regression models with SHR >1.14 as the dependent variable, log IL-10, IL-10/TNF-α ratio, log CXCL10, and log IFN-γ were separately included together with age, sex, presence of diabetes, CRP, and severity of disease as covariates." (PMID 36059840, 2022). "Compared with previous studies, we evaluated immunologic indices, including IL-6, TNF-α, IL-4, IL-10, TGF-β1 levels, and regulatory T cells, in addition to general diabetes evaluation." (PMID 35725652, 2022). "On the other hand, IL-10/TNF-α, IL-10/IL-6, IL-10/IL-12, Gal-3/TNF-α, Gal-3/IL-6, and Gal-3/IL-12 (p = 0.001) were significantly higher (p < 0.05) in gonarthrosis with diabetes mellitus." (PMID 36141752, 2022).
diabetes (continued). "Interestingly, the correlation analysis of gut microbiota with diabetes-induced intestinal inflammation showed that Deferribacteres were positively related to FBG, pro-inflammatory cytokines such as TNF-α, IL-1β, IL-6, and IL-17, which were negatively associated with IL-10 and TGF-β." (PMID 36045662, 2022). "In NOD mice, helminth parasites as well as their products prevent diabetes via the induction of CD4+ Treg and the production of IL-10." (PMID 35113966, 2022). "The effects of depletion of IL-10 in diabetic microglia were then assessed in a mouse model for cerebral atherosclerosis, ApoE (−/−) mice that receive STZ to develop diabetes." (PMID 35935990, 2022). "ROC analysis was used to identify cut-off values of ApoA1, IL-10 and TNF-α in diabetes patients with foot ulcers." (PMID 35836916, 2022). "Overall in patients with diabetes, an imbalance towards M1 macrophages increases expression of pro-inflammatory cytokines like TNF-α and decreases IL-10 production (r = −0.224, p = 0.004) by M2 cells, and delays wound healing." (PMID 35836916, 2022). "In this study, the serum levels of IL-2, IL-10, and INF-γ were higher in COVID-2019 patients with diabetes than both patients with IFG and patients with normal sugar." (PMID 33490288, 2021). "Diabetes significantly triggered the increases of pro-inflammatory cytokines (TNF-α and IL-6) and decrease of the anti-inflammatory cytokines (IL-10)." (PMID 34497508, 2021). "Our results showed that BDC2.5+Il-10-/- NOD mice displayed robust and accelerated diabetes development." (PMID 34394099, 2021). "Animals administered with Salmonella ΔmsbB along with the combination of PI+TGFβ+IL10 and anti-CD3 antibody were prevented from developing diabetes (Log-rank Mantel-Cox, p = 0.006) for more than 100 days post-treatment compared to control mice." (PMID 34108968, 2021). "In the presence of diabetes, the basal secretion of IL-1β, IL-27, IL-33, and SDF-1 is augmented while that of IL-10, IL-12, and IL-8 was downregulated." (PMID 34566972, 2021). "Diabetes related biomarkers: GIP, GLP-1, leptin, glucagon and inflammatory cytokines: IL-4, IL-5, IL-10, IL-12, IFN-g and TNF-α were significantly affected by HFB diet compared to HF diet." (PMID 34441468, 2021). "Importantly, INU treatment could decrease TNF-α and IL-6 but increase IL-10 in diabetes mice." (PMID 33390939, 2020). "It has been reported that monocyte CD163 expression is reduced in diabetes and CD163 is strongly induced by IL-10 in macrophages." (PMID 32879134, 2020). "As IL-10 played important protective role in diabetes, we utilized the CRISRP/dCas9 activation system to overexpress IL-10 in BM-MSCs." (PMID 31164920, 2019). "These M2r macrophages express programmed death ligand 1 (PD-L1) and PD-L2, secrete IL-10 and TGF-β, suppress T-cell proliferation and are capable of preventing diabetes in NOD mice." (PMID 29725003, 2018). "In diabetics, the systemic levels of LTB4, TNF-α, IL-6, IL-10, IL-12 and IFNγ were increased as well as the frequency of pro-inflammatory monocytes (CD11b+Ly6ChighLy6G−) compared to healthy mice." (PMID 30242286, 2018). "The levels of cytokines (e.g., IL-6, IL-1β, IL-10, and IL-12) and chemokines (e.g., MCP-1, MIG, and RANTES) are perturbed in MDMs derived from patients with diabetes, both before infection and in response to Mtb infection." (PMID 29513874, 2018). "IL-10 signaling inhibition is reversible and can be restored via blockade of TI-IFN/IFN-R interaction, paralleling with the resulting delay in diabetes onset and reduced severity." (PMID 30061883, 2018). "TLR-mediated effects of probiotics involve immune-regulatory cytokines such as interleukin IL-10 and transforming growth factor (TGF)-β and some regulatory T cells, under the experimental conditions that result in protection from spontaneous diabetes." (PMID 28538869, 2017). "Expression of TNF-α, IFN-γ, and IL-10 within the islets all enhance NOD insulitis and diabetes development." (PMID 29497709, 2017).
diabetes (continued). "IL-10, as an important immunomodulatory cytokine, is described to reduce IFN-γ in pancreatic β cells and prevent diabetes progression." (PMID 29033948, 2017). "In comparison with severe diabetes controls, MSC infusion reduced insulitis, decreased pancreatic TNF-α, and increased IL-10 and TGF-β1 expression in NOD mice." (PMID 27905403, 2016). "A combination therapy (CT) of LL-PINS+IL-10 with a short-course of subtherapeutic doses anti-CD3 Abs reversed diabetes in 59% of treated mice in comparison to 25% with anti-CD3 monotherapy and 15% when using LL-PINS+IL-10 alone." (PMID 25185797, 2014). "In this study, we conducted combined intervention of IL-10 and IGF-1 in NOD mice with diabetes at onset stage and evaluated its protective effects on the residual islet β- cells, hoping to provide a theoretical basis for early clinical treatment of T1D." (PMID 24663217, 2014). "The enhanced pro-inflammatory burden in diabetic mice is also reflected by the overall increased levels of circulating plasma cytokines (IL-6, IFN-γ, IL-12p70, IL-1β, IL-10, TNFα, OPN and sVCAM-1) after 8 weeks of diabetes." (PMID 23755169, 2014). "PDGF levels positively correlated with maternal IL-10 levels and leukocyte and platelet counts (all r<0.335), suggesting a link to the inflammatory process rather than diabetes itself." (PMID 40698658, 2025). "In those individuals with type 1 and type 2 diabetes who harbored detectable vaccine‐specific T cells, they displayed an unfocused, tolerogenic phenotype characterized by increased expression of IL‐10 and IL‐13 compared with people without diabetes." (PMID 41367201, 2025). "The prediction model incorporated diabetes, FET, and IL-10 as the variables." (PMID 41426569, 2025). "After adjusting for hypertension, diabetes, triglyceride levels, gender, and age, Student t tests covariance confirmed significant differences in the enrichment levels of TWEAK, TNF-α, IL-10, and IL-4 of patients in case group (PTWEAK = .017, PTNF-α < .001, PIL-10 = .010, PIL-4 = .016)." (PMID 40629651, 2025). "In non-obese diabetic (NOD) mice, depletion of IL-10-producing Bregs accelerates diabetes onset and worsens β-cell destruction, while adoptive transfer of Bregs delays disease progression." (PMID 40370441, 2025). "Mechanistically, diabetes induction resulted in kidney inflammation by elevating levels of tumor necrosis factor-alpha (TNF-α), transforming growth factor beta (TGF-β), and interleukin 6 (IL-6), while reducing IL-10 levels and increasing the IL-6/IL-10 ratio." (PMID 38510054, 2024). "Specifically, only IL-10 + B cells, not whole B-cell populations or IL-10 − B-cell subsets, were able to suppress autoreactive T-cell activation ex vivo and prevent the diabetes progression in vivo." (PMID 39014283, 2024). "Intriguingly, we found that NOD1 depletion in hematopoietic cells does not exert any influence on diabetes-induced alterations in TNFα and IL10, underscoring the intricate nature of the inflammatory response operating within the diabetic retina." (PMID 38336763, 2024). "A higher IL-6/IL-10 ratio was found in patients with diabetes compared to the group without diabetes at T0 and T1, whereas an increased IFN-γ/IL-10 ratio was only found at T1 in patients with diabetes in comparison to the group without diabetes." (PMID 39253540, 2024). "Concerning the group of patients without diabetes it was verified not only positive significant correlations between levels of IL-10 and IL-6 or IFN-γ but also a negative significant correlation between the levels of IL-6 and PMP, at baseline (T0)." (PMID 39253540, 2024). "Our results showed that patients with diabetes presented higher IL-10 and TNF-α gene expression compared to those without diabetes, suggesting an increased inflammatory activity." (PMID 37189738, 2023).
diabetes (continued). "Thus, our aim was to explore whether individuals with diabetes and normal or prolonged segmental gastrointestinal transit times exhibit differences in the systemic levels of the inflammatory cytokines (interleukin (IL)-6, IL-8, IL-10, interferon (IFN)-γ, and tumour necrosis factor (TNF)-α)." (PMID 37189645, 2023). "We aimed to investigate whether IL‐10 and its upstream factors exert an impact on MCI in type 2 diabetes mellitus (T2DM) patients." (PMID 37532673, 2023). "Among subjects with diabetes, those with TIR ≤ 70% had higher levels of IL-1α, IL-1β, IL-6, IL-12 p70, IL-16, LIF, M-CSF, MCP-1, MCP-3, RANTES, TNF-α, TNF-β, and b-NGF, and lower levels of IL-1α, IL-4, IL-10, GM-CSF, and MIF than individuals with TIR > 70%." (PMID 37893217, 2023). "A negative correlation was found for IL-10 expression and the age of patients with diabetes, and the time of diagnosis of the disease." (PMID 37189738, 2023). "The main contribution of this research was that diabetes enhances the lung injury and inflammation in rats due to elevated levels of TNF-α, IL-6, and IL-1β and lower levels of IL-10, lower SOD and GPx activity, TAC levels, and increased MDA and NO levels in tissue and BALF." (PMID 37520024, 2023). "There was a positive correlation between IL-10 RQ and HbA1c (p < 0.001), a negative correlation between IL-10 and the age of subjects with diabetes (p = 0.029), and time of diagnosis of the disease (p = 0.036)." (PMID 37189738, 2023). "Our data demonstrated that diabetes repressed IL-10 expression in the adipose tissue; however, nondiabetic plasma was able to induce IL-10 expression in SVFs isolated from diabetic mice." (PMID 35883204, 2022). "The results showed that the GMP intervention group could further reduce the inflammatory reaction induced by diabetes by reducing the levels of IL-6, TNF-α, and CRP and increasing IL-10." (PMID 35399678, 2022). "IL-10 may lead to the expansion of CD16+ monocytes, thus diabetes treatment could efficiently combat pro-inflammation by CD16 + monocytes under septic conditions." (PMID 36687421, 2022). "Neither interleukin 10 nor interferon gamma were significantly related to diabetes mellitus duration (P. value = 0.267 and 0.298, respectively." (PMID 36443718, 2022). "Comparing the immunological makers in both groups, subjects in the DFU group showed a lower ApoA1 and IL-10 but higher TNF-α when compared to patients with diabetes without foot ulcers (Group- I)." (PMID 35836916, 2022). "Also, the combination therapy of ΔmsbB (PI+TGFβ+IL10) with anti-CD3 mAb to prevent and revert new-onset diabetes in NOD mice was tested." (PMID 34108968, 2021). "It seems that diabetic patients diagnosed with SARS-CoV-2 infection had higher values of IL-2, IL-6, IL-10, and interferon gamma than those without diabetes mellitus (NDM) or impaired fasting glucose (IFG)." (PMID 34201473, 2021). "However, diabetes also increased anti‐inflammatory factor level (IL‐10), and FGF1 treatment further enhanced the level of IL‐10." (PMID 33788387, 2021). "To assess the role of IL-10 in diabetes protection observed in BDC2.5+ NOD mice, we first monitored the natural history of type 1 diabetes development in BDC2.5+Il-10+/+ NOD mice and BDC2.5+Il-10-/- NOD mice." (PMID 34394099, 2021). "We also observed that anti-inflammatory markers (as in the case of IL-10 and IL-4) were more expressed in the circulating leukocytes of obese individuals with or without diabetes when compared to lean individuals." (PMID 35069589, 2021). "In patients with and without diabetes, metformin has been shown to favorably alter inflammatory mediators, including interleukin 6 (IL-6), TNFα, to possibly boost interleukin 10 (IL-10), and suppress the C-C motif chemokine ligand." (PMID 34367059, 2021). "No human trials administering or targeting IL-10 have so far been reported, but studies using the non-obese diabetic (NOD) mouse model of T1D found that IL-10 has protective effects on diabetes development." (PMID 32967650, 2020).